CAMKK2 (calcium/calmodulin dependent protein kinase kinase 2)
Diseases named in the same sentence as CAMKK2 in open-access papers (continued):
Sharing a sentence is not in itself a finding about the gene and the disease.
prostate carcinoma (continued). "Accordingly, host deletion of Camkk2 impaired the growth of syngeneic murine prostate tumors in vivo, confirming nonautonomous roles for CAMKK2 in prostate cancer." (PMID 35741020, 2022). "Therefore, the overall objective of this paper was to interrogate how Zyflamend activates AMPK in a model of castrate-resistant prostate cancer and the roles LKB1 and CaMKK2 play in that activation." (PMID 29914450, 2018). "However, the Pb-Cre;Ptenf/f GEMM, as a relatively benign prostate cancer model, does not allow CAMKK2 to be studied in the context of metastasis or progression to highly aggressive subtypes such as neuroendocrine prostate cancer (NEPC)." (PMID 35741020, 2022). "Moreover, while CAMKK2 is known to regulate systemic metabolism, whether CAMKK2’s effects on whole-body metabolism would impact prostate cancer progression and/or related comorbidities is not known." (PMID 35741020, 2022).
Insulin resistance (18 papers, 2012 to 2025). Increased resistance towards insulin, that is, diminished effectiveness of insulin in reducing blood glucose levels. "Myeloid-specific Camkk2 deficiency protected mice from high fat diet-induced obesity, insulin resistance and liver steatosis." (PMID 40945690, 2025). "•Myeloid-specific CAMKK2 deficiency in mice prevents diet-induced fat accumulation, insulin resistance, and hepatosteatosis." (PMID 40945690, 2025). "The loss of Camkk2 has been shown to protect mice from obesity, insulin resistance, and glucose intolerance induced by high-fat diets." (PMID 39708266, 2025). "Consequently, we demonstrate that myeloid-specific Camkk2 deficient mice are protected from high fat diet-induced whole-body obesity, insulin resistance and hepatosteatosis." (PMID 40945690, 2025). "For example, liver-specific deletion of CaMKK2 in mice protects against high-fat diet-induced glucose intolerance and insulin resistance, whereas genetic liver-specific AMPK activation has the same effect." (PMID 39268917, 2024). "Here were found many genes whose expression positively correlates with obesity, insulin resistance, type-2 diabetes and chronic inflammation, such as Irs2, Angptl4, Lepr, Camkk2 and Tbk1." (PMID 37957359, 2023). "Obese patients with low folate intake, showed lower methylation levels of CAMKK2, a condition correlated with increased insulin resistance." (PMID 33585535, 2020). "CAMKK2 null mice developed obesity, insulin resistance, and less glucose tolerance with standard chow whereas displayed a considerably smaller increase in adiposity and adipocyte size with high-fat diet compared with WT mice by regulating NPY and therefore affecting appetite." (PMID 38469147, 2024). "CAMKK2 plays role in diet-induced obesity, glucose intolerance and insulin resistance." (PMID 37293508, 2023). "Also, complex relationships between dietary folate intake, CAMKK2 DNAm and expression levels, and insulin resistance were reported." (PMID 37836535, 2023). "Camkk2 null mice are protected from obesity, insulin resistance, and glucose intolerance." (PMID 24759943, 2014). "Consequently, mice with a myeloid specific deletion of Camkk2 are protected from high fat diet-induced obesity, insulin resistance and hepatosteatosis, highlighting CAMKK2 as an attractive therapeutic target for the treatment of inflammatory and metabolic diseases." (PMID 40945690, 2025).
Obesity (17 papers, 2014 to 2026). Accumulation of substantial excess body fat. "This has been further reflected in the involvement of CAMKK2 in several metabolic diseases characterized by the manifestation of dysregulated mitochondrial function as part of their pathogenic process, including, for example, cancer, obesity, diabetes, neurodegeneration, and NAFLD." (PMID 34563205, 2021). "Our data highlight the CaMKK2/AMPK pathways as a key mediator of anti-obesity effects after setmelanotide treatment." (PMID 41601974, 2026). "The aim of this study was to determine the contribution of CAMKK2 to the regulation of inflammation and systemic metabolism during diet-induced obesity." (PMID 40945690, 2025). "Our data establish CAMKK2 as an important regulator of macrophage function and putative therapeutic target for treating obesity and related metabolic disorders." (PMID 40945690, 2025). "Adipocytes acted by Calmodulin affect energy metabolism to reduce obesity.The activation of CaMKK2 in hypothalamic neurons can regulate the feeding behavior to reduce obesity." (PMID 31195699, 2019). "•CAMKK2 is an attractive therapeutic target for treating obesity and related metabolic disorders." (PMID 40945690, 2025). "Then, we selected 5 variants in genes previously reported to be associated with obesity, adipogenesis or linked to obesity-associated traits by genome-wide association studies (SLC25A5, AIM2, SNX16, CAMKK2 and PDE11A) for further analysis to identify candidate MOVs." (PMID 38469147, 2024). "Notably, we observed simultaneous anti-cancer effects with improvements in liver pathology and insulin sensitivity in our HFD/obesity-driven TRAMP model following Camkk2 ablation." (PMID 35741020, 2022). "Crucially, administration of setmelanotide restored CaMKK2/AMPK activity, reactivated MC4R neurons, and normalized appetite and feeding behavior during fasting-refeeding and the long-term treatment of obese rats (60% reduction in food intake), ultimately reversing obesity (23% weight loss)." (PMID 41601974, 2026). "Hence, the development of clinically relevant CAMKK2 inhibitors may fill a large unmet clinical need for new therapies for inflammatory diseases, including chronic co-morbid conditions of obesity." (PMID 40945690, 2025). "Interestingly, CaMKK2 impinges the activation program of macrophages, and consequently, genetic ablation of Camkk2 attenuates the detrimental inflammatory response induced by bacterial endotoxin or obesity." (PMID 34712241, 2021). "In addition to regulating metabolism-related functions, it has become a common view that the activation of CaMKK2 in hypothalamic neurons could also effectively regulate the feeding behavior of the body to reduce obesity." (PMID 31195699, 2019). "In summary, our findings indicate that setmelanotide treatment effectively activates PVN MC4R by upregulating the CaMKK2/AMPK pathways, thereby inhibit hyperphagia and reverse obesity in HO rats." (PMID 41601974, 2026).
breast cancer (16 papers, 2011 to 2025). A primary or metastatic malignant neoplasm involving the breast. "We originally reported that CaMKK2 is significantly expressed in macrophages associated with the breast cancer microenvironment." (PMID 34712241, 2021). "Here, we demonstrate that CaMKK2 is also expressed in tumor-associated myeloid cells, as well as in human breast cancer cells." (PMID 31164648, 2019). "Moreover, we have previously shown that deletion of CaMKK2 in the host restrains mammary cancer growth, and this phenomenon was associated with increased accumulation of T cells in the tumor microenvironment and prevented by depletion of CD8+ T cells." (PMID 34712241, 2021). "Thus, we hypothesized that CaMKK2 may impact the function of mammary tumor-associated myeloid subsets to influence tumor pathobiology." (PMID 31164648, 2019). "Prior work demonstrated that myeloid-specific deletion of Camkk2 impaired syngeneic tumor growth in preclinical models of breast cancer." (PMID 40945690, 2025). "More recently, we demonstrated that CaMKK2 is a key regulator of the immune-suppressive microenvironment in breast cancer and blockade of this enzyme attenuates tumor growth in a CD8+ T cell-dependent manner." (PMID 34712241, 2021). "More recently, we have demonstrated that CaMKK2 expressed in myeloid cells is an important regulator of the immunosuppressive breast cancer microenvironment and blockade of this kinase in the host cells inhibits tumor growth." (PMID 34712241, 2021). "CAMKK2 knockout mice had attenuated growth of grafted mammary tumors, which the authors attribute to a reduction in immunosuppressive activities." (PMID 31941153, 2020). "A recent publication demonstrated that CAMKK2 plays a key role in the regulation of the immune-suppressive microenvironment in breast cancer." (PMID 31941153, 2020). "The goal of this study, therefore, was to investigate the extent to which CaMKK2 impacts immune cell repertoire and function in the microenvironment of mammary tumors." (PMID 31164648, 2019). "To probe the potential significance of CaMKK2 expression in human breast cancer, we analyzed CaMKK2 expression in two well-curated breast cancer tissue microarrays (Vienna and Roswell Park)." (PMID 31164648, 2019). "The expression of CaMKK2 within immune cells that infiltrate mammary tumors was further assessed in a syngeneic model of breast cancer." (PMID 31164648, 2019). "To test this hypothesis, we used Camkk2−/− mice in conjunction with a metastatic model of mammary tumor cells." (PMID 40036145, 2025). "Previously, a different cancer cell-extrinsic role was reported in breast cancer involving the regulation of the anti-tumor immune response through CAMKK2’s functions in macrophages, and more recently in a preclinical model of lymphoma, myeloid-derived suppressor cells (MDSCs)." (PMID 35741020, 2022). "Of note, changes in the TIL repertoire observed in lymphoma models resemble those originally described in mammary tumors growing in Camkk2-/- compared to WT mice, indicating that in these two models of tumors deletion of Camkk2 in the host trigger a similar anti-tumor effector mechanism." (PMID 34712241, 2021). "Based on these results, we hypothesize that, besides breast cancer, CaMKK2 expressed in the host cells might have a more general function in the mechanism regulating the anti-tumor immune response." (PMID 34712241, 2021). "Lastly, whereas we have previously reported that an increased frequency of TAM II+ and cDC accumulate in mammary tumors growing in Camkk2-/- mice compared to WT, we didn’t find statistically significant differences in the frequency of TAM II+/cDC in lymphoma microenvironment (data not shown)." (PMID 34712241, 2021). "Thus, two chemically distinct, selective CaMKK2 antagonists demonstrated similar inhibitory effects in mouse models of breast cancer." (PMID 31164648, 2019).
breast cancer (continued). "Thus, we conclude that ablation of Camkk2 within myeloid cells is sufficient to attenuate the growth of E0771 mammary tumors in immune-competent mice." (PMID 31164648, 2019). "The impact of disrupting host CaMKK2 expression on mammary tumor growth was next evaluated." (PMID 31164648, 2019). "Analysis of the combined data confirmed the negative association of CaMKK2 expression with LA breast cancer (OR = 0.3; p-value = 0.017; Fisher’s exact test) and elevated expression of CaMKK2 in TN tumors (OR 4.1; p-value = 0.0026; Fisher’s exact test)." (PMID 31164648, 2019). "Thus, we reasoned that the decreased growth of mammary tumors observed in Camkk2−/− mice might reflect an attenuation of immunosuppressive activities or an enhancement of immune-stimulatory functions of myeloid cells within tumors." (PMID 31164648, 2019). "However, we ruled out the involvement of this complex in CaMKK2 biology as myeloid cell-specific knockdown of ERRα failed to impact the growth of mammary tumors in the MMTV model." (PMID 31164648, 2019). "Thus, we used this compound to evaluate the impact of CaMKK2 inhibition on the growth of E0771, 4T1, and Met1 cell-derived tumors propagated in syngeneic hosts, as well as in the MMTV- PyMT spontaneous model of mammary carcinoma." (PMID 31164648, 2019). "Therefore, the CaMKK2/AMPK signal might not be involved in the cell survival mechanisms in human breast cancer SK-BR-3 cells, even though PCP4/PEP19 knockdown reduced AMPK phosphorylation." (PMID 25153723, 2014).
Hepatic steatosis (12 papers, 2017 to 2025). Steatosis is a term used to denote lipid accumulation within hepatocytes. "TRPC3 loss robustly aggravated the alcohol-induced hepatic steatosis and liver injury in mouse liver; this was associated with the suppression of Ca2+/calmodulin-dependent protein kinase kinase 2 (CAMKK2)/AMP-activated protein kinase (AMPK) and dysregulation of genes related to lipid metabolism." (PMID 39871879, 2024). "Germline deletion of Camkk2 protects mice from high-fat diet-induced weight gain, insulin resistance, hepatic steatosis, and hepatocellular carcinoma." (PMID 40945690, 2025). "Liver-specific TRPC3 silencing aggravates alcohol-induced hepatic steatosis and liver injury by suppressing Ca2+/calmodulin-dependent protein kinase kinase 2 (CAMKK2)/AMPK signaling pathway." (PMID 39871879, 2024). "CAMKK2 is involved in ethanol-induced hepatic steatosis, and treatment with caffeic acid, a phytochemical in coffee, increases its mRNA and protein expression, thereby reducing alcohol-mediated damage in mice." (PMID 36389068, 2022). "Nevertheless, the multiple mechanisms of action of CAMKK2 underscore the potential of CAMKK2 inhibitors for the treatment of cancer as well as other diseases such as diabetes, fatty liver disease, and more." (PMID 35741020, 2022). "Leveraging the information from our in vivo pharmacokinetic analysis of STO-609, we demonstrate that pharmacological inhibition of CaMKK2 reverses the hallmarks of hepatic steatosis in two mouse models of NAFLD." (PMID 28924233, 2017). "Furthermore, pharmacological inhibition of CaMKK2 with STO-609 has been reported to reverse key features of hepatic steatosis in two mouse models of fatty liver disease." (PMID 39268917, 2024). "Its activation prevents hepatic steatosis by inhibiting gene and protein expression of SREBP-1c through signaling cascade activation that involves Gq/11, calcium/calmodulin-dependent protein kinase kinase 2 (CaMKK) and AMP-activated protein kinase (AMPK)." (PMID 33525643, 2021).
lung carcinoma (11 papers, 2015 to 2025). "Our study elucidates the molecular mechanisms underlying the crosstalk between the CaMKK2 signaling pathway and CSCs in lung cancer, which can aid in the development of novel treatment strategies." (PMID 39076120, 2024). "Using TCGA cohorts, we also confirmed that CaMKK2 expression was associated with the survival rate of patients with lung cancer, with a higher CaMKK2 expression associated with a decreased patient survival rate." (PMID 39076120, 2024). "To demonstrate the clinical significance of TIPRL and CaMKK2 in lung CSCs, we evaluated the expression of two proteins in CSCs freshly isolated from tissues of patients with lung cancer." (PMID 39076120, 2024). "Simultaneously, CaMKK2 activated downstream AMPK, finally providing anti-anoikis and pro-metastatic signals in LKB1-deficient lung cancer, resulting in a poor prognostic outcome for LKB1-deficient lung cancer patient." (PMID 37829798, 2023). "The mechanism involves the enhancement of its substrate AMPK binding by the GDH1 product α-KG that activates CamKK2 to generate energy, resulting in anti-anoikis and ultimately promoting metastasis of lung cancer." (PMID 36091049, 2022). "Finally, the correlation between TIPRL and CaMKK2 expression was assessed among CSCs isolated from patients with lung cancer and in the data of patients with lung cancer from the TCGA cohort." (PMID 39076120, 2024). "Our findings suggest that the interaction between TIPRL and CaMKK2, which are both highly expressed in lung CSCs and bulk tumor cells, could be related to the poor prognosis of patients with lung cancer." (PMID 39076120, 2024). "However, the role of CAMKK2 in the pathogenesis and prognosis of lung cancer has yet to be clarified." (PMID 36606188, 2022). "Thus, TIPRL and the CaMKK2 signaling axis may be promising targets for overcoming drug resistance and reducing metastasis in lung cancer." (PMID 39076120, 2024). "For instance, α-KG can bind to calcium/calmodulin-dependent protein kinase kinase 2 (CAMKK2) and stimulate the activity of AMPK, a substrate of CAMKK2, thereby inhibiting the mTOR pathway, balancing redox status and ultimately reactivating anoikis resistance signaling in LKB1-deficient lung cancer." (PMID 35530337, 2022). "A study in lung cancer showed that GDH1 promoted anoikis resistance and metastatic of tumors through CamKK2 activation." (PMID 38226966, 2024). "The positive feedback loop consisting of CREB and TIPRL induces the sustained activation of the CaMKK2‐CaMK4‐CREB axis as a driving force and upregulates the expression of stemness‐ and survival‐related genes, promoting tumorigenesis in patients with lung cancer." (PMID 39076120, 2024). "Additionally, a CRE‐driven reporter assay showed that CaMKK2 depletion in several lung cancer cell lines resulted in decreased CREB activity, whereas CaMKK2 overexpression increased it." (PMID 39076120, 2024). "The mRNA level of CaMKK2 was higher in patients with SCLC and LUAD versus adjacent normal tissues; in CSCs isolated from several lung cancer cell lines (e.g., A549, H460, H1299, and H1793) versus non‐CSCs; and in CSCs freshly isolated from tissues of patients with lung cancer versus non‐CSCs." (PMID 39076120, 2024).
diabetes (10 papers, 2018 to 2024). "Fibroblast growth factor 21 ameliorates diabetes-induced endothelial dysfunction in mouse aorta via activation of the CaMKK2/AMPKα signaling pathway." (PMID 33029194, 2020). "Inhibition of CAMKK2 reduces neuronal apoptosis and neuroinflammation in neonatal hypoxic–ischemic encephalopathy and germinal matrix hemorrhage in rodents and may facilitate the expression of adiponectin, an adipokine that protects against diabetes and atherosclerosis." (PMID 36389068, 2022). "Taken together, the data suggest that CaMKK2 may be an upstream regulator determining the activity of AMPKα and mediating the alleviating effects of FGF21 on diabetes-induced oxidative stress and endothelial dysfunction." (PMID 31511499, 2019).
hepatocellular carcinoma (10 papers, 2019 to 2024). A malignant tumor that arises from hepatocytes. "CaMKK2 was significantly upregulated in hepatocellular carcinoma (HCC) and negatively correlated with the survival rate of HCC patients." (PMID 31744495, 2019). "The inhibition of CAMKK2 protects against prostate cancer, hepatocellular carcinoma (HCC) and metabolic disorders induced by a high-fat diet." (PMID 35399533, 2022). "In hepatocellular carcinoma, cannabinoid-induced ER stress may lead to AMP-activated protein kinase (AMPK) and calcium/calmodulin-dependent protein kinase kinase 2 (CAMKK2) activation, which is also considered a factor leading to autophagic cell death." (PMID 33383838, 2020).
melanoma (10 papers, 2011 to 2025). A malignant, usually aggressive tumor composed of atypical, neoplastic melanocytes. "Some studies have demonstrated the upstream regulatory mechanism of ferroptosis in melanoma before, and we previously reported that CAMKK2 and miR-21-3p were critical regulators of melanoma cell ferroptosis through the regulation of AMPK-Nrf2 and TXNRD1, respectively." (PMID 36429010, 2022). "Analysis of the TCGA-SKCM and GTEx datasets revealed elevated expression of NF2, SUZ39H1, CDC25A, GLRX5, and CISD3 in melanoma tissues, in contrast with the reduced expression of VDR, PPARD, CAMKK2, NT5DC2, and CHP1A." (PMID 40860143, 2025). "Our previous investigations proved that miR-21-3p and CAMKK2 regulated the TXNRD1 and AMPK-Nrf2 axes, respectively, to mediate the execution of melanoma cell ferroptosis." (PMID 36429010, 2022). "Similarly, the kinase Calcium/Calmodulin-Dependent Protein Kinase Kinase 2 (CAMKK2), which functions through the AMPK-NRF2 axis, has been shown to negatively regulate ferroptosis in melanoma cells." (PMID 41235238, 2025).